GALK2 (galactokinase 2)
Description:
Acts on GalNAc. Also acts as a galactokinase when galactose is present at high concentrations. May be involved in a salvage pathway for the reutilization of free GalNAc derived from the degradation of complex carbohydrates.
Synonyms: GK2
Tractability: Small molecule: a structure with a bound ligand is known; it has a high-quality binding pocket. PROTAC: ubiquitination databases record sites on it; its protein half-life has been measured.
Gene: Protein-coding gene on chromosome 15 (49,155,656 to 49,367,869, forward strand). Ensembl gene ENSG00000156958.
Subcellular location (Human Protein Atlas): Cytosol; Nucleoplasm
Gene Ontology:
Molecular function: galactokinase activity; N-acetylgalactosamine kinase activity; ATP binding; kinase activity; phosphotransferase activity, alcohol group as acceptor
Biological process: carbohydrate metabolic process; carbohydrate phosphorylation; galactose metabolic process
Cellular component: cytoplasm
Genetic constraint (gnomAD): Loss-of-function variants: 26 observed, 35.89 expected, observed/expected ratio (o/e) 0.72, 90% interval 0.53 to 1. The upper end of that interval is the gene's LOEUF score, 1, which puts it in group 4 of 6, group 1 being the genes least tolerant of losing a copy. Missense variants: 438 observed, 434.63 expected, observed/expected ratio (o/e) 1.01, 90% interval 0.93 to 1.09. Synonymous variants: 142 observed, 165.81 expected, observed/expected ratio (o/e) 0.86, 90% interval 0.75 to 0.98.
Homologues: Orthologues: chimpanzee GALK2 (99% identical), macaque GALK2 (94% identical), pig GALK2 (92% identical), rabbit GALK2 (91% identical), dog GALK2 (90% identical), mouse Galk2 (89% identical), guinea pig GALK2 (88% identical), rat Galk2 (88% identical), tropical clawed frog galk2 (73% identical), zebrafish galk2 (65% identical), Drosophila melanogaster Galk (44% identical), Caenorhabditis elegans tag-96 (40% identical). Paralogues in human: GALK1 (29% identical), MVK (17% identical).
Diseases named in the same sentence as GALK2 in open-access papers:
GALK2 is named in the same sentence as 6 diseases in open-access papers, as found by Europe PMC text mining. Sharing a sentence is not in itself a finding about the gene and the disease. The quoted sentences say what the papers report.
Becker muscular dystrophy (1 paper, 2022). Becker muscular dystrophy (BMD) is a neuromuscular disease characterized by progressive muscle wasting and weakness due to degeneration of skeletal, smooth and cardiac muscle. "From the identified disease-specific genes, four genes (ANK3, GALK2, ZBTB45 and PLXNA1) were previously reported to be involved in the pathogenesis of DMD and Becker Muscular Dystrophy (BMD), a milder form of DMD." (PMID 35388741, 2022).
IgA nephropathy (1 paper, 2024). "There is evidence indicating significant alterations in the level of H3K4me3 of fc receptor like 4 (FCRL4) and galactokinase 2 (GALK2) in peripheral blood mononuclear cells of IgA nephropathy patients." (PMID 39595187, 2024).
prostate carcinoma (1 paper, 2012). A carcinoma that arises from epithelial cells of the prostate gland. "This study demonstrates the applicability of lentiviral-based shRNA for conducting phenotypic screens and identifies MAP3K11, DGKD, ICK, CIT, GALK2, and PSKH1 as regulators of prostate cancer cell growth." (PMID 22761715, 2012). "It is plausible that the requirement for CIT, GALK2, and PSKH1 varies depending upon the tumorigenic state since the mRNA levels of these kinases increase as prostate cancer progresses." (PMID 22761715, 2012). "This study further demonstrates the applicability of lentiviral based shRNA for conducting phenotypic screens to identify targets involved in a variety of biological processes, and establishes MAP3K11, DGKD, ICK, CIT, GALK2, and PSKH1 as regulators of prostate cancer cell growth." (PMID 22761715, 2012).
GALK2 also shares sentences with these, for which no sentence is quoted: dental caries (1 paper); infection (1); kidney disease (1).